PTH (parathyroid hormone)
Diseases named in the same sentence as PTH in open-access papers (continued):
Sharing a sentence is not in itself a finding about the gene and the disease.
parathyroid adenoma (continued). "An Australian study published in 2020, which enrolled patients with PHPT (n=555), found a strong positive correlation between preoperative PTH levels and parathyroid adenoma weight (rho=0.602, p<0.001)." (PMID 39040613, 2024). "Parathyroid adenomas are benign tumors, and while they do secrete PTH, it is essential to recognize that these cells have an affected stimulus-secretion coupling." (PMID 38554052, 2024). "Despite the intricate PTH–Vitamin D–FGF23 axis, surgical removal of parathyroid gland adenoma maintained a statistically significant decrease in PTH concentration even after considering Vitamin D levels." (PMID 38785509, 2024). "Parathyroid adenoma leads to excessive secretion of parathyroid hormone (PTH), disrupting calcium and phosphate balance." (PMID 39427404, 2024). "Combined with Tc-99m-MIBI scintigraphy and abnormal PTH and blood calcium levels, the consideration was given to the lesion in the sternocleidomastoid muscle as an ectopic parathyroid adenoma." (PMID 38957316, 2024). "We previously reported that C-PTH fragments are directly secreted from parathyroid adenomas and have a longer half-life than 1–84 PTH in patients with PHPT." (PMID 38662187, 2024). "Due to her severe hypercalciuria, persistent elevation of PTH, and frequent colicky stone attacks a Tc-99m Sestamibi parathyroid scan was performed which demonstrated a 9 × 6 × 12-mm ectopic parathyroid adenoma within the superior mediastinum." (PMID 39055046, 2024). "She subsequently underwent surgical parathyroid adenoma resection 10-month after her initial presentation, prompted by the triad of rapidly progressing kidney stone disease, elevated PTH levels, and the presence of an ectopic adenoma." (PMID 39055046, 2024). "Further research is needed to explore the rare occurrence of parathyroid adenoma in patients with normocalcemia, normal parathyroid hormone (PTH) levels, normal vitamin D levels, and normal renal function tests." (PMID 39697923, 2024). "Intraoperative PTH measurement in venous blood is highly recommended after the surgical removal to improve accuracy in identifying the ectopic location of parathyroid adenomas and have proof of its radical excision." (PMID 39712793, 2024). "Another case discussed a patient with dysphagia and odynophagia but normal calcium and PTH levels, where an infarcted parathyroid adenoma was eventually identified and surgically treated." (PMID 39427404, 2024). "80–85 % of primary HPT cases are secondary to a chief cell parathyroid adenoma, understandably so as chief cells constitute the main source of parathyroid hormone (PTH)." (PMID 38971030, 2024). "Radiologic assessments indicated a potential parathyroid adenoma, yet her serum calcium, vitamin D, and parathyroid hormone levels were largely normal." (PMID 39697923, 2024). "This typically involves conducting blood tests to assess calcium, phosphate, PTH, and vitamin D levels, as well as imaging studies to identify the presence of a parathyroid adenoma." (PMID 37790151, 2023). "The optimal cutoff values for diagnosing parathyroid adenoma based on lesion volume, blood flow distribution, PTH concentration, E-min, E-mean, and E-max were 0.475 cm3, level 1.5, 281.85 ng/L, 11.620 kPa, 16.125 kPa, and 17.995 kPa, respectively." (PMID 37713846, 2023). "While this technique can allow a precise determination of the site of elevated PTH levels, it is unable to differentiate between parathyroid hyperplasia and parathyroid adenoma." (PMID 36563301, 2023). "Patients with parathyroid adenoma and carcinoma exhibited higher preoperative parathyroid hormone (PTH) and serum calcium levels than normal individuals, both of which were highest in carcinoma patients." (PMID 37121965, 2023). "In the last decade, it was demonstrated that [18F]FCh uptake of parathyroid adenomas strongly correlates with preoperative PTH serum level." (PMID 40729208, 2023).
parathyroid adenoma (continued). "Few studies have indicated a positive correlation between serum calcium and PTH levels and adenoma volume in patients with parathyroid adenomas." (PMID 37892003, 2023). "This case report highlights the importance of preoperative localization and intraoperative PTH monitoring in evaluating patients with PHPT in the setting of multiple synchronous parathyroid adenoma." (PMID 37908206, 2023). "The results indicated that the volume, blood flow, PTH concentration, and elastic modulus of the joint focus were of high value in diagnosing parathyroid adenoma." (PMID 37713846, 2023). "VDR and PTH gene expression in parathyroid adenomas ranges from very low to high compared to normal tissue where PTH and VDR are highly expressed." (PMID 37223014, 2023). "In our patient, the cause of most symptoms and laboratory results were preliminarily attributed to the excessive secretion of PTH in the right lower parathyroid adenoma with corresponding results of neck US, MRI, and MIBI in the local hospital." (PMID 37415163, 2023). "Until now, it was considered that parathyroid hormone levels would drop to about 50% of the original baseline value measured 10 min after parathyroid adenoma excision." (PMID 35407623, 2022). "The patient was operated and on the examination of the removed tissue, the histopathological examination concluded to an atypical parathyroid adenoma, and the post‐operatory PTH level dropped significantly to 152 pg/ml." (PMID 36578799, 2022). "PTH of functioning PC is far more increased than the normal limit and even much more than patients with parathyroid adenoma which was reported to be 136 ± 6 pg/ml(1.9 times of normal range)." (PMID 36193301, 2022). "More than a decade later, aged 45 years, a recurrence of PHPT was diagnosed (corrected calcium 2.69 mmol/L, normal range 2.1-2.6 mmol/L; PTH 104 pg/mL, normal range 15-68 pg/mL) and a second parathyroid adenoma was resected." (PMID 35323929, 2022). "And the LMD-LC-MS/MS spectra successfully identified the amyloid fibril protein in parathyroid adenomas as PTH." (PMID 36704039, 2022). "The proband (II.2) presented aged 32 years with PHPT (corrected calcium 2.92 mmol/L, normal range 2.16-2.45 mmol/L; PTH 12.4 pmol/L, normal range 0.8-8.0 pmol/L) and a left superior parathyroid adenoma was resected via minimally invasive surgery." (PMID 35323929, 2022). "A diagnosis of parathyroid adenoma and PHPT was made based on the elevated parathyroid hormone levels and cervical ultrasonography indicated right inferior parathyroid adenoma." (PMID 36401406, 2022). "We report the usefulness of robotic resection for ectopic mediastinal parathyroid adenoma with PTH monitoring." (PMID 35987641, 2022). "The concentration of preoperative PTH reflects the weight of the parathyroid adenoma, this concordance has already been reported by other studies." (PMID 36268338, 2022). "The initial manifestation of parathyroid carcinoma is usually quite acute, and the serum calcium and parathyroid hormone (PTH) levels are often higher than with parathyroid adenoma." (PMID 36188029, 2022). "In our country, according to state hospital prices, cost of PTH measurement is approximately 1 dollar, and parathyroid adenoma surgery cost is 210 dollars." (PMID 36211265, 2022). "Serum calcium and serum PTH levels in patients with parathyroid carcinoma are significantly higher than those in parathyroid adenoma." (PMID 34420520, 2021). "Intraoperative PTH measurement is recommended to confirm successful resection of the hyperfunctioning parathyroid adenoma." (PMID 34209340, 2021). "In parathyroid adenoma, calcium levels are usually equal to or less than 11 mg/dl and PTH levels are high." (PMID 34462682, 2021). "Regarding their immunophenotype, most parathyroid adenomas are positive for chromogranin A, PTH, and GATA3." (PMID 33269427, 2021).
parathyroid adenoma (continued). "US-guided FNA of the suspected lesion with subsequent PTH measurement in the washout was first applied in the 1980s, with a sensitivity of 70100% and specificity of 75100% for parathyroid adenomas." (PMID 34020602, 2021). "This case demonstrates the importance of evaluation of cystic components for PTH levels and if confirmed should be treated as a parathyroid adenoma." (PMID 34646632, 2021). "Compared with parathyroid adenoma and hyperplasia, carcinoma cases presented higher serum PTH, calcium, and ALP levels (P<0.001) and larger tumor sizes (P<0.001)." (PMID 33716964, 2021). "PHPT can be effectively and safely treated by ultrasound-guided MWA, as proven by drop in serum PTH and reduction in the volume of parathyroid adenomas." (PMID 34925241, 2021). "The likely effects of caffeine on PTH release were determined by the batch incubation of the patient’s parathyroid adenoma cells." (PMID 32983662, 2020). "Based on the data reviewed, it is evident that caffeine can be used as adjuvant therapy in parathyroid adenomas to suppress the PTH level until parathyroidectomy is performed." (PMID 32983662, 2020). "If PTH level is inappropriate (normal or elevated), a neck ultrasonography (US) and Tc99m-sestamibi scintigraphy will be required to localize parathyroid adenoma or hyperplasia." (PMID 31979085, 2020). "Increased circulating levels of PTH may also be caused by parathyroid carcinoma (though in rare cases (1-2%)), but more often because of diffuse parathyroid hyperplasia (around 15%), and single or multiple autonomously functioning parathyroid adenomas (up to 85%)." (PMID 32283730, 2020). "pHPT was defined by the presence of elevated serum calcium levels with inappropriate normal or increased parathyroid hormone (PTH) serum levels or histopathological evidence of parathyroid adenoma or hyperplasia." (PMID 31979085, 2020). "Compared to hyperplasia, parathyroid adenomas often present with a higher increase in the level of serum PTH." (PMID 32983662, 2020). "Left video-assisted thoracoscopic surgery (VATS) was performed to excise this ectopic parathyroid adenoma leading to normalisation of Ca (2.46 mmol/l, 9.9 mg/dl) and PTH (6.4 pmol/l) levels." (PMID 31797261, 2020). "This is consistent with previous studies, which reported that parathyroid adenomas have weaker PTH mRNA intensity relative to normal parathyroid tissue, and that disease severity is dependent on tumor weight." (PMID 30832348, 2019). "The KL and PTH genes, which play significant roles in calcium regulation, were down-regulated in parathyroid adenoma compared with normal parathyroid tissue samples." (PMID 30832348, 2019). "Upregulation of phospholipid/Ca2+-dependent choline kinase has been shown to be related to PTH secretion in parathyroid adenoma." (PMID 29516131, 2018). "Parathyroid hormone (PTH) assays on the needle washout of FNA specimen of suspected parathyroid tissue are further tools of localizing parathyroid adenomas." (PMID 28280507, 2017). "Two out of three parathyroid adenomas tested displayed minimal suppression of PTH abundance in response to elevated calcium concentrations, while the same conditions provoked a larger, 2.7-fold decrease in a third tumor." (PMID 27537691, 2016). "We observed that a majority of parathyroid adenomas exhibited weaker PTH immunoreactivity andPTH mRNA intensity compared with corresponding normal parathyroid rim." (PMID 26865585, 2016). "have conducted studies on 198 patients who underwent surgery for PHP, and have found high levels of preoperative serum calcium, PTH, ALP, BUN, large parathyroid adenomas, and old age as risk factors for development of HBS." (PMID 27737322, 2016). "c) The intraoperative PTH serum value (after removal of ectopic parathyroid adenoma) was 31 pg/ml (80% below from baseline)." (PMID 24685256, 2014). "Possible effects of caffeine on PTH secretion were determined by batch incubation studies of human parathyroid adenoma cells." (PMID 23788688, 2013).
parathyroid adenoma (continued). "Difficulties or unexpected outcomes can be encountered in patients with renal insufficiency and when PTH spikes with consecutive delayed PTH reduction occur by unintended manipulation of parathyroid adenomas during mobilization." (PMID 24044556, 2013). "Serum calcium and parathyroid hormone levels decreased postoperatively and histopathology confirmed the diagnosis of a parathyroid adenoma." (PMID 23484975, 2013). "The expression of ADORA1, ADORA2A, and PTH after 30-minute caffeine treatment of cultured parathyroid adenoma cells was evaluated by qRT-PCR." (PMID 23788688, 2013). "After a mean follow-up of 12 month (range 10–18 months), all PHPT patients had parathyroid adenoma based on pathological examination, showing normalization of serum calcium and PTH levels as normal urinary calcium and phosphorous excretion." (PMID 22719761, 2012). "This case of parathyroid crisis, with very high serum calcium and parathyroid hormone levels, is a rare presentation of parathyroid adenoma with cystic degeneration." (PMID 22840059, 2012). "Excision of parathyroid adenoma was followed by the predicted fall in Intraoperative serum PTH concentration of >50% in ten patients." (PMID 21197437, 2010). "Intraoperative parathyroid hormone (IOPTH) measurement has recently been introduced as a useful adjunct in confirming the successful excision of a parathyroid adenoma." (PMID 21197437, 2010). "These alternative modes of PTH hypersecretion revealed distinct actions of the CaSR and the VDR that may underlie the divergent secretory patterns seen in different types of parathyroid adenomas." (PMID 40492090, 2025). "Finally, the serum calcium and PTH levels were also related to the volume of the parathyroid adenoma." (PMID 39941666, 2025). "A 5.4 g right inferior type E parathyroid adenoma was excised with normalization of PTH levels." (PMID 40342445, 2025). "The mechanism behind the increased accumulation of radiotracers in parathyroid adenoma cells remains unclear, but it is suspected to be due to increased cell proliferation and elevated production of preProPTH (a precursor of PTH)." (PMID 39941666, 2025). "Moreover, the presence of lymphocyte infiltrates in parathyroid adenomas was correlated with higher levels of PTH, potentially indicating a cytokine mediated change in the endocrine activity of parathyroid cells." (PMID 40529359, 2025). "Another possible explanation, consistent with this case, is that the presence of a moderately active parathyroid adenoma may lead to the suppression of PTH secretion from the other parathyroid glands." (PMID 40821457, 2025). "Given this scenario, this study aimed at evaluating whether the collection of PTH from the internal jugular veins bilaterally helps to identify parathyroid adenoma laterality in patients with PHPT." (PMID 40209343, 2025). "In orthotopic parathyroid adenomas, PTH-WO values were 2592.0 pg/mL (493.0–5,000.0) in the left inferior region, 767.0 pg/mL (549.0–4,861.5) in the left superior, 1312.5 pg/mL (558.5–3,849.75) in the right inferior, and 971.0 pg/mL (250.75–1,563.25) in the right superior." (PMID 41036141, 2025). "Another aspect of interest in our case, which differentiates it from other casereports of brown tumors, is the degree of elevation of calcium and PTH, which hadthe treating team suspecting parathyroid carcinoma, until the tumor was proven to bea benign giant parathyroid adenoma on pathology." (PMID 39700332, 2024). "Or, could certain expressed PTH molecules in parathyroid adenoma scenarios prove difficult to assay using conventional study methods?" (PMID 39697923, 2024). "PHPT, a condition often associated with parathyroid adenoma, is influenced by a range of factors, including genetic predisposition and biochemical factors (such as vitamin D status and PTH but not calcium levels)." (PMID 39040613, 2024).
parathyroid adenoma (continued). "Further, they reported no intragenic mutations in the pre-pro-PTH coding region in either the parathyroid adenoma or matched blood DNA samples from the patient they studied." (PMID 39697923, 2024). "MicroRNA (miRNA) profiling may serve as a helpful adjunct in distinguishing parathyroid adenoma (PAd) from PC and provide further insight into regulatory pathways involved in PTH release and parathyroid tumorigenesis." (PMID 35205624, 2022). "During exploration an ‘intended intraoperative manipulation’ of parathyroid adenomas through mechanical stimulation may lead to increased PTH excretion." (PMID 36515670, 2022). "Interestingly, the same lncRNA was also detected in a PTH-overexpressing parathyroid adenoma (PA) from another patient, suggesting that its expression is closely related to the expression of the nearby PTH gene." (PMID 35618021, 2022). "Additionally, 20 min after extirpation of the parathyroid adenoma, PTH was on average 13.84 units lower than at 10 min after extirpation (p < 0.001)." (PMID 35407623, 2022). "The tumor was positive for PTH and was diagnosed as an ectopic mediastinal parathyroid adenoma." (PMID 35987641, 2022). "They speculated that the formation of amyloid in a subset of parathyroid adenomas resulted from inappropriate PTH production." (PMID 36704039, 2022). "In addition, selective parathyroid hormone venous sampling was effective tool regionalize or lateralize the parathyroid adenoma." (PMID 33993327, 2021). "We investigated whether single parathyroid adenoma size can be estimated using preoperative parathyroid hormone (PTH), calcium, and phosphate in patients with PHPT." (PMID 33928428, 2021). "Parathyroid tumors are rare endocrine neoplasms affecting 0.1–0.3% of the general population, comprising slow-growing benign PTH-secreting adenomas in almost 100% of cases, atypical parathyroid adenomas in about 1.2–1.3% of cases, and extremely rare malignant carcinoma in less than 1% of cases." (PMID 34681865, 2021). "It is reported that larger parathyroid adenomas secrete PTH at a lower rate than lighter adenomas." (PMID 33256695, 2020). "With the guidance of ultrasound, PTH value was tested by the parathyroid puncture and further application of carbon nanoparticles was provided to check whether parathyroid adenomas would be stained black." (PMID 32283730, 2020). "Our study revealed that SI of parathyroid lesions as well as serum calcium, parathyroid hormone levels, and B-mode US features may help to predict the atypical parathyroid adenoma." (PMID 31751311, 2019). "Interestingly, the PTH gene exhibited reduced expression, despite the higher serum PTH levels in patients with parathyroid adenomas." (PMID 30832348, 2019). "This inconsistency may be explained by the notion that cystic adenomas arise from acute necrosis and hemorrhage in parathyroid adenomas within a relatively short time, which results in the release of large amounts of PTH into the circulation." (PMID 30123260, 2018). "Parathyroid hormone elevation and imaging exams confirmed bleeding from a parathyroid adenoma." (PMID 30473899, 2018). "Cdc73+/−, Cdc73+/L/PTH-Cre and Cdc73L/L/PTH-Cre mice developed parathyroid tumours, which had nuclear pleomorphism, fibrous septation and increased galectin-3 expression, consistent with atypical parathyroid adenomas, from 9 months of age." (PMID 28288139, 2017). "While the number of cases was limitedin this study, the PTH immunoreactivity in atypical adenomas (Fisher’s exact test:P = 0.002) and carcinomas (Fisher’s exact test: P =0.003) was more frequently scored as stronger in comparison with parathyroid adenomas." (PMID 26865585, 2016). "In this study, we document individual cellular patterns of calcium responsiveness within biochemically and cytopathologically verified intact parathyroid adenoma tissue and relate these behaviors to parathyroid hormone production and cumulative tumor calcium sensitivity." (PMID 27537691, 2016).